GFAP (glial fibrillary acidic protein)
Diseases named in the same sentence as GFAP in open-access papers (continued):
Sharing a sentence is not in itself a finding about the gene and the disease.
morphine dependence (2 papers, 2015 to 2024). Strong dependence, both physiological and emotional, upon morphine. "Post hoc tests indicated an increase (p < 0.05) of GFAP-IR during morphine dependence and withdrawal." (PMID 26164717, 2015). "Furthermore, in the prefrontal cortex and cerebellum, pre-exposure to fluoride altered the response to morphine dependence (compared to fluoride exposure alone), resulting in additional increases in GFAP mRNA expression of 33% and 54%, respectively (p < 0.05)." (PMID 38255899, 2024).
mucositis (2 papers, 2017 to 2019). Mucositis is inflammation and damage of the mucous membranes lining the mouth and other parts of the gastrointestinal (GI) tract. "We also demonstrated that 5-FU upregulates S100B protein expression in GFAP-positive cells during mucositis, suggesting that EGCs are an important source of S100B on this model." (PMID 30679569, 2019).
myotonic dystrophy type 1 (2 papers, 2021 to 2023). Steinert disease, also known as myotonic dystrophy type 1, is a muscle disease characterized by myotonia and by multiorgan damage that combines various degrees of muscle weakness, arrhythmia and/or cardiac conduction disorders, cataract, endocrine damage, sleep disorders and baldness. "First, neuronal injury markers, including neurofilament light (NF-L), total tau, glial fibrillary acidic protein (GFAP) and ubiquitin C-terminal hydrolase (UCH-L1), were compared between individuals with and without adult-onset myotonic dystrophy type 1 (DM1)." (PMID 35126292, 2021).
neonatal encephalopathy (2 papers, 2022 to 2023). "UCHL1 and GFAP have been found to have neuroprognostic importance in infants with neonatal encephalopathy." (PMID 36428450, 2022).
nerve sheath tumor (2 papers, 2021 to 2022). "In our study, we histopathologically reevaluated 79 canine nerve sheath tumors and assessed their reactivity for the immunohistochemical markers Sox10, claudin-1, GFAP, CNPase, and Ki-67." (PMID 35622732, 2022).
Neurodegeneration (2 papers, 2021 to 2022). Progressive loss of neural cells and tissue. "MMXM inhibited GFAP overexpression in retinal Müller cells in diabetic rats and protected against early diabetic retinal neurodegeneration." (PMID 33927618, 2021).
neuroendocrine carcinoma (2 papers, 2019 to 2022). A malignant neuroendocrine neoplasm composed of cells containing secretory granules that stain positive for NSE and chromogranin. "In human specimens, the most striking increase in GFAP expression was within the neuroendocrine carcinoma; however, reactive astrocytes were identified throughout the BAT and the BTB of adenocarcinoma and carcinoma." (PMID 31695842, 2019).
neurofibromatosis type 1 (2 papers, 2019 to 2023). A clinically heterogeneous, neurocutaneous genetic disorder characterized by cafe-au-lait spots, iris Lisch nodules, axillary and inguinal freckling, and multiple neurofibromas. "For example, a hallmark feature of post-mortem Neurofibromatosis Type 1 (NF1) (MIM: 162200) patient forebrains and mouse models of NF1 is an increased number of GFAP+ reactive astrocytes." (PMID 31017896, 2019).
neurosyphilis (2 papers, 2024 to 2025). Infection of the brain or spinal cord by Treponema pallidum. "Recently, observational studies revealed that cerebrospinal fluid (CSF) GFAP, as a valuable potential diagnostic biomarker for neurosyphilis, had a sensitivity of 76.60% and specificity of 85.56%." (PMID 38216970, 2024).
neurothekeoma (2 papers, 2024 to 2025). A benign neoplasm arising from nerve sheaths. "Although the terms neurothekeoma and nerve sheath myxomas were used interchangeably, they are now described as distinct entities, with the later exhibiting positive immunohistochemistry for S100 and Sox-10 and moderate/diffuse reactivity to glial fibrillary acidic protein (GFAP) and CD57." (PMID 39057135, 2024).
non-small cell lung carcinoma (2 papers, 2022 to 2025). A group of at least three distinct histological types of lung cancer, including non-small cell squamous cell carcinoma, adenocarcinoma, and large cell carcinoma. "Pembrolizumab-associated GFAP meningoencephalomyelitis was reported in a patient with non-small cell lung cancer (NSCLC)." (PMID 40936919, 2025). "Biomarkers of neurodegeneration, NfL, GFAP, tau and UCHL1 were measured in a cohort of up to 88 subjects at baseline and 21 days after the first of six cycles of paclitaxel and carboplatin chemotherapy, administered as therapy for the treatment of non-small cell lung cancer." (PMID 36114333, 2022).
Noonan syndrome (2 papers, 2016 to 2021). Noonan Syndrome (NS) is characterized by short stature, typical facial dysmorphism and congenital heart defects. "A recent report identified that a mouse model for the Noonan syndrome mutation RAF1-L613V exhibits an increased GFAP expression in the cortex and hippocampus." (PMID 34222248, 2021).
pancreatic adenocarcinoma (2 papers, 2014 to 2020). "Pancreatic adenocarcinoma sections showed positive staining for GFAP localized to stellate-shaped cells and their cytoplasmic processes." (PMID 24847445, 2014). "Furthermore, by analyzing the publicly accessible datasets for patients with pancreatic adenocarcinoma (PAAD), we found that the gene expression of three typical SC markers, GFAP, S100B, and SRY-box transcription factor 10 (SOX10), was significantly associated with that of several EMT markers." (PMID 32308766, 2020).
pancreatitis (2 papers, 2011 to 2021). Inflammation of the pancreas. "To assess whether hippocampal inflammation may play a role in pancreatitis-induced mechanical hypersensitivity, we semi-quantitated hippocampal GFAP expression, as a marker of astroglial reactivity 7 days after cerulean administration." (PMID 34049483, 2021). "Expression of stellate cell markers CELSR3, PBX1 and GFAP was observed in BMD cancer-associated PaSCs, however cancer-associated, but not pancreatitis-associated BMD PaSCs, expressed the cancer PaSC specific marker CELSR3." (PMID 22022519, 2011).
perineurioma (2 papers, 2011 to 2022). A usually benign perineurioma not associated with a nerve, arising from the soft tissues. "Four MNSTs (6.0%) were strongly immunoreactive for claudin-1 and negative for Sox10 and GFAP and were accordingly classified as MNSTs with perineurial differentiation or malignant perineurioma." (PMID 35622732, 2022).
phenylketonuria (2 papers, 2015 to 2022). Phenylketonuria (PKU) is the most common inborn error of amino acid metabolism and is characterized by mild to severe mental disability in untreated patients. "Numerous GFAP(+)/MBP(+) cells are reported in a mouse model of phenylketonuria, which is associated with central hypo-mylination, and there is strong evidence for astrocyte production from NG-2 cells following traumatic injury, ischemia and spinal cord injury." (PMID 26106302, 2015). "In addition, there was a significant association of GFAP concentrations with current plasma tyrosine concentrations (r = −0.482, p = 0.036), a biochemical marker in phenylketonuria, and the retinal inner nuclear layer volume (r = 0.451, p = 0.04)." (PMID 36247773, 2022).
pineal tumors (2 papers, 2009 to 2024). "Of these pineal parenchymal tumors, 12 of 13 demonstrated immunoreactivity for synaptophysin, currently the most widely used marker of pineal tumors, in >75% of tumor cells and 12 of 13 demonstrated immunoreactivity for GFAP, a glial marker, in <5% of tumor cells." (PMID 19936203, 2009).
progressive ataxia (2 papers, 2012 to 2014). "Overexpression of GFAP is a feature of reactive astrocytes observed in the cerebellum of ataxic rats and in patients with progressive ataxia." (PMID 25338046, 2014). "Up-regulation of GFAP is a feature of reactive astrocytes that was reported in the cerebellum of ataxic rats, and patients suffering from progressive ataxia." (PMID 23150735, 2012).
Pruritus (2 papers, 2022 to 2025). Pruritus is an itch or a sensation that makes a person want to scratch. "Several studies have reported that pruritus-induced mice show increased GFAP expression in the SDH." (PMID 40443235, 2025). "We found that DHS inhibited GFAP expression, thus indicating that DHS inhibits astrocyte activation in chloroquine-treated mice, thereby reducing pruritus." (PMID 40443235, 2025). "It should be mentioned that TNCB induces local inflammation, and therefore, the GFAP upregulation may not be specific for pruritus, but is a consequence of the inflammation." (PMID 35269508, 2022).
pulpitis (2 papers, 2023 to 2024). Inflammation of the dental pulp. "At 24 h after pulpitis induction, the expression of CGRP-positive neurons and GFAP-positive SGCs in the TG significantly increased, reaching a peak at 72 h and lasting for six weeks." (PMID 40531313, 2024). "After pulpitis induction, the expression of CGRP-positive neurons and GFAP-positive soluble guanylate cyclase (SGC) in the TG significantly increased." (PMID 40531313, 2024). "After administering Cur by intraperitoneal injection, the expression levels of Toll-like receptor 4 (TLR4), CGRP, glial fibrillary acidic protein (GFAP), fractalkine (CX3CL1), Tumor necrosis factor (TNF-α), and other factors were examined in the TG of pulpitis-induced rats." (PMID 40531313, 2024).
radiculopathy (2 papers, 2020 to 2023). Disease involving a spinal nerve root (see spinal nerve roots) which may result from compression related to intervertebral disk displacement; spinal cord injuries; spinal diseases; and other conditions. "When compared with radiculopathy controls, CSF GFAP and pNF-H levels were higher in patients with spinal cord tethering (p ≤ 0.05)." (PMID 32588294, 2020). "The peripheral clinical picture in patients with GFAP-Abs is heterogeneous and dominated by cranial nerve involvement and radiculopathy, while inflammatory demyelinating polyradiculoneuropathy, sensory neuronopathy, or length-dependent axonal polyneuropathy were more rarely found." (PMID 37540278, 2023). "In the current cohort, GFAP levels but not UCH-L1 were significantly higher in tethered cord patients compared with radiculopathy." (PMID 32588294, 2020).
Retinal atrophy (2 papers, 2016 to 2024). A nonspecific term denoting wasting, especially as a result of degeneration, of the retinal pigment epithelium (RPE) and neurosensory retinal cells. "Retinal atrophy, loss of RGCs, and extensive glial fibrillary acidic protein (GFAP) immunoreactivity has been observed in MS and EAE20,23,32,33." (PMID 39402114, 2024). "In our diseased human retinal tissues, we saw extensive GFAP immunoreactivity that corresponded with retinal atrophy." (PMID 27660801, 2016).
retinoblastoma (2 papers, 2009 to 2021). A malignant tumor that originates in the nuclear layer of the retina. "Finally we find that CRX is a new sensitive and specific marker for retinoblastoma and pineal parenchymal tumors that should be useful in the diagnostic evaluation of pineal masses when used as part of a panel of immunohistochemical markers including synaptophysin and GFAP." (PMID 19936203, 2009).
sensory impairment (2 papers, 2020 to 2025). "Secondly, more importantly, the expression of GFAP and inflammatory cytokines IL‐1β, IL‐6, and TNF‐α were increased both in PD patients with and without sensory impairment." (PMID 31828965, 2020).
Sjögren syndrome (2 papers, 2021 to 2025). "This phenomenon has been recognized in specific contexts, including MOG antibody-associated disease (MOGAD), GFAP astrocytopathy, Sjögren’s syndrome, and lupus myelitis." (PMID 41451231, 2025).
Spastic paraplegia (2 papers, 2025). Complete loss of the ability to move the lower limbs accompanied by spasticity of the lower limbs. "In addition, a focused literature review was performed using PubMed, Scopus, Web of Science, and Google Scholar with the search terms “Alexander disease,” “GFAP gene,” “late-onset,” “spastic paraplegia” and “GFAP variant p/Gly18Val”." (PMID 41303265, 2025).
subependymoma (2 papers, 2024 to 2025). Subependymoma is a rare and slow growing type of ependymoma, often presenting in middle-aged adults, found more commonly in men than in women, usually located in the fourth and lateral ventricles and manifesting with variable symptoms including headache, nausea, and loss of balance. "In contrast, PFA tumors were more variable, often displaying subependymoma-like GFAP-rich low-cellularity areas and a broader range of EMA profiles." (PMID 41464145, 2025). "The majority of cases presented histopathological and immunohistochemical findings (GFAP immunopositivity without expression of Olig2 or SOX10) suggestive of an ependymal differentiation or subependymoma-like features (microcystic changes)." (PMID 38581034, 2024).
teratocarcinoma (2 papers, 2014 to 2025). A germ cell tumor characterized by the presence of an embryonal carcinoma component and a teratoma component. "However, some studies have indicated that taurine treatment was associated with a reduced level of GFAP in rats after 3-nitropropionic acid exposure in the xenotransplantated neurons derived from the human teratocarcinoma cell line." (PMID 24885898, 2014). "The teratoma contained NF-expressing axonal structures, Olig2-positive oligodendrocyte-like cells, GFAP-expressing astrocytic cells and isolated NSE-expressing cells, whereas only GFAP-expressing cells were detected in the teratocarcinoma." (PMID 40217475, 2025). "GFAP positive astrocytes in avian teratocarcinomas have previously only been detected in an emu." (PMID 40217475, 2025).
Thiamine deficiency (2 papers, 2012 to 2022). Thiamine deficiency is a condition that occurs due to not enough thiamine (vitamin B1). "Thiamine deficiency increases glial fibrillary acidic protein (GFAP) and inflammation in parallel with neuronal loss." (PMID 36275801, 2022). "Astrocytes as measured by GFAP are a major target of thiamine deficiency." (PMID 36275801, 2022).
abdominal aortic aneurysm (1 paper, 2018). Enlargement and ballooning of the vessel that supplies arterial blood to the abdomen, pelvis and legs. "In another study of open thoraco-abdominal aortic aneurysm (TAAA) surgery increased GFAP levels postoperatively were associated with delayed onset of paraplegia." (PMID 30367354, 2018).
acute angle closure glaucoma (1 paper, 2021). "In experimental animal models characteristic of acute angle closure glaucoma and other OHT models, like MB model, EVO model, or genetic model of POAG, each showed increased expression of GFAP." (PMID 34943212, 2021).
adenoid cystic carcinoma (1 paper, 2009). A malignant tumor arising from the epithelial cells.
Adult onset (1 paper, 2010). Onset of disease manifestations in adulthood, defined here as at the age of 16 years or later. "Analysis of the GFAP gene revealed a heterozygous missense mutation, c.827G>T, p.R276L, which was already shown to be pathogenic in a case of pathologically proven hereditary adult-onset ALX." (PMID 20359319, 2010). "We have described here a new patient with sporadic adult-onset ALX, and have identified a heterozygous missense mutation in the GFAP gene, c.827G>T, p.R276L, which was already shown to be pathogenic in a case of pathologically proven hereditary adult-onset ALX." (PMID 20359319, 2010).
alcohol addiction (1 paper, 2022). "These alterations were accompanied by an increase of glial fibrillary acidic protein (GFAP) and allograft inflammatory factor 1 (AIF-1) in the medial prefrontal cortex (mPFC) and HIP, respectively, crucial brain areas for the development of alcohol addiction." (PMID 35682586, 2022).
angiomyolipoma (1 paper, 2017). A neoplasm with perivascular epithelioid cell differentiation often associated with tuberous sclerosis. "We employed a nestin or GFAP-Cre driver to remove the floxed Tsc1 allele from the NSCs and early and late neuronal progenitors, respectively, since both promoters are active in LAM and angiomyolipoma." (PMID 29184052, 2017).
angiosarcoma (1 paper, 2018). A malignant tumor arising from the endothelial cells of the blood vessels. "Lastly we used an endothelial cell-specific Cre driver, Tie2-CreER and found that the TKO combination also developed angiosarcomas, albeit with a broader tissue distribution when compared to the GFAP-CreER mice." (PMID 29872503, 2018).
anorexia nervosa (1 paper, 2021). A disorder most often seen in adolescent females characterized by a refusal to maintain a minimally normal body weight, an intense fear of gaining weight, a disturbance in body image, and, in postmenarcheal females, the development of amenorrhea. "Recent studies showed that GFAP+ astrocyte cell density is reduced in the central nervous system of an experimental anorexia nervosa model." (PMID 35011927, 2021).
Apathy (1 paper, 2022). Apathy is a quantitative reduction of interest, motivation and the initiation and persistence of goal-directed behavior, where often the accompanying emotions, thoughts, and social interactions are also diminished. "We tested the hypothesis that elevated CSF GFAP levels, reflecting astrocyte activation, would be correlated with depressed mood and apathy in PWH." (PMID 37205974, 2022). "Both virally suppressed and unsuppressed PWH contributed to the relationship between GFAP and apathy: for suppressed PWH r=0.126, p=0.302, N=69; for not suppressed r=0.262, p=0.0016, N=142; interaction p=0.388." (PMID 37205974, 2022). "In a multivariable regression predicting apathy scores, the interaction between age and GFAP was not significant(p=0.888), while both main effects of both GFAP (p=0.0442) and age (p=0.0197) were significant." (PMID 37205974, 2022).
arachnoid cyst (1 paper, 2024). Intracranial or spinal cavities containing a cerebrospinal-like fluid, the wall of which is composed of arachnoidal cells. "In addition, the expression of GFAP can be used for differential diagnosis from ECs and arachnoid cysts." (PMID 39759143, 2024).
artery stenosis (1 paper, 2018). "Transgenically altered mice overexpressing the transcription factor Nrf2 (GFAP-Nrf2) and wild type littermates were subjected to bilateral carotid artery stenosis or sham surgery." (PMID 30135571, 2018).
asphyxia (1 paper, 2015). A state of general hypoxia and hypercapnia (abnormally elevated carbon dioxide (CO2) levels in the blood), resulting in acidosis, which affects all tissues in the body. "Serum GFAP is not altered in the UCB samples of infants with perinatal asphyxia, with or without clinical and electrographic HIE, compared to normal controls." (PMID 26733938, 2015). "Therefore, our aim was to examine the use of GFAP as an early clinical marker of HIE severity in full-term neonates by determining expression in umbilical cord blood (UCB) samples from healthy control infants, infants with perinatal asphyxia, and infants with HIE." (PMID 26733938, 2015).
atherosclerosis (1 paper, 2023). A disease characterized by the build-up of fatty material and calcium deposition in the arterial wall resulting in partial or complete occlusion of the arterial lumen. "Interestingly, DAA subcluster 7 had enrichment of lipid and atherosclerosis pathway genes, and GFAP/BODIPY double staining revealed neutral lipid accumulation in astrocytes in PS19-E4 mice." (PMID 37957317, 2023).
autonomic neuropathy (1 paper, 2023). An inherited or acquired peripheral neuropathy affecting the autonomic nervous system. "Conversely, when patients have unexplained autonomic neuropathy, GFAP antibody testing should be performed to confirm the diagnosis." (PMID 36647033, 2023).